SNORA70J (small nucleolar RNA, H/ACA box 70J)
Gene: Small nucleolar RNA gene on chromosome 5 (171,366,118 to 171,366,252, forward strand). Ensembl gene ENSG00000206909.
Gene Ontology:
Biological process: RNA processing
Cellular component: nucleolus
Homologues: Orthologues: chimpanzee SNORA70 (99% identical), macaque SNORA70 (95% identical). Paralogues in human: SNORA70H (94% identical), SNORA70G (93% identical), SNORA70 (92% identical), SNORA70B (91% identical), SNORA70C (91% identical), SNORA70I (90% identical), SNORA70 (90% identical), SNORA70 (89% identical), SNORA70E (89% identical), SNORA70 (88% identical), SNORA70D (87% identical), SNORA70 (87% identical), and 14 more.
Diseases named in the same sentence as SNORA70J in open-access papers:
SNORA70J is named in the same sentence as 1 disease in open-access papers, as found by Europe PMC text mining. Sharing a sentence is not in itself a finding about the gene and the disease. The quoted sentences say what the papers report.
ovarian carcinoma (1 paper, 2022). A malignant neoplasm originating from the surface ovarian epithelium. "Among them, the expression abundance of snoRA70J, alike its host gene, is very low in ovarian cancer tissues." (PMID 35187852, 2022).